CTBP2 (C-terminal binding protein 2)
Diseases named in the same sentence as CTBP2 in open-access papers (continued):
Sharing a sentence is not in itself a finding about the gene and the disease.
cancer (55 papers, 2010 to 2025). A tumor composed of atypical neoplastic, often pleomorphic cells that invade other tissues. "CTBP1 and CTBP2 (C-terminal binding proteins) play critical roles in transcriptional repression and are frequently implicated in cancer progression." (PMID 40362431, 2025). "CtBP2’s involvement in various physiological processes and its overexpression in cancers make it an attractive therapeutic target." (PMID 38932279, 2024). "Future research should investigate the development of CtBP2-specific inhibitors and their potential in cancer therapy." (PMID 38932279, 2024). "Functional redundancy between CTBP1 and CTBP2 is supported by the Cancer Dependency Map (DEPMAP) database." (PMID 38748792, 2024). "The interaction between Tiam1 and C-terminal binding protein 2 (CTBP2) promotes the proto-oncogenic function of CTBP2 and leads to cancer cell migration." (PMID 37563730, 2023). "We demonstrated that knockdown of CtBP2 significantly reduced the nuclear/cytoplasm partitioning of Bcl-xL and invasion and metastasis of the cancer cells induced by Bcl-xL overexpression in vivo." (PMID 37163116, 2023). "CTBP2 can enhance the invasion and migration of cancer cells, and through some signaling pathways, it can regulate the cell cycle, and apoptosis, associated with tumor suppression." (PMID 37563730, 2023). "MDSCs upregulated miR-101 expression and further repressed C-terminal binding protein-2 (CtBP2), a corepressor gene targeting stem cell core genes directly, and thus promoted the stemness and invasion of cancer cells." (PMID 35634311, 2022). "We next performed CtBP2-silencing in MDA-MB231 cancer cells by stable RNA interference of CtBP2 (shCtBP2 cells)." (PMID 34680207, 2021). "For example, CtBP2 associates with KLF8 (Kruppel-like factor 8) to activate the expression of Tiam1 (T-cell lymphoma invasion and metastasis 1), thereby promoting cancer cell migration." (PMID 32140068, 2020). "Both NCOR2 and CTBP2 were hypermethylated in liver and blood of WD patients and function as transcriptional co-repressors that are dysregulated in cancer." (PMID 30709419, 2019). "On the other hand, genes responsible for the negative regulation of transcription including Meis homeobox 2 and C-terminal binding protein 2 were both up-regulated in L6 and L7 tomato extract treated cancer cells." (PMID 28448505, 2017). "This phenomenon suggests a reduction of cell adhesion in the knockdown cancer cells, similar to what we have reported for the CtBP2-KD cancer cells." (PMID 26871283, 2016). "By day 7, when the control cancer cells were becoming very confluent, all the Pinin and CtBP1 knockdown cell lines showed, with CtBP2-KD cells a lesser degree, excessive detachment from the culture plates." (PMID 26871283, 2016). "In an ovarian carcinoma model MDSCs triggered miR-101 expression in cancer cells, subsequently miR-101 silenced corepressor gene C-terminal binding protein-2 (CtBP2) which resulted in increased cancer stemness and dissemination." (PMID 27886105, 2016). "Another finding about the interaction between Pinin and CtBP proteins is that Pinin levels were reduced in both CtBP1-KD and CtBP2-KD cancer cells." (PMID 26871283, 2016). "Given the intimate interactions between Pinin and CtBP proteins, it is not surprising that the RNA processing aberrations were also observed in CtBP1-KD and CtBP2-KD cancer cells." (PMID 26871283, 2016). "We have reported that miRNA-101 increased cancer cell stemness by repressing the corepressor gene C-terminal binding protein-2 (CtBP2)." (PMID 27557510, 2016). "Pinin co-localized and physically interacted with transcriptional corepressor C-terminal binding proteins, CtBP1 and CtBP2, in the nuclei of cancer cells." (PMID 26871283, 2016). "The Pinin knockdown cell lines shared significant overlap of differentially expressed genes and RNA splicing aberrations with CtBP1 knockdown and in a lesser degree with CtBP2 knockdown cancer cells." (PMID 26871283, 2016).
cancer (continued). "SNAIL1 was also found to interact with C-terminal binding protein 2 (CtBP2) a transcriptional co-repressor that promotes cancer cell migration and invasion (EMT) by inhibiting multiple tumor suppressor genes." (PMID 26633513, 2015). "miR-101 has been associated with inflammation as a negative regulator of inducible costimulator (ICOS) and cancer cell stemness as a negative regulator of the corepressor C-terminal binding protein-2 (CtBP2)." (PMID 25886994, 2015). "As reported most recently, MDSCs induce stemness and tumorigenicity in proximal cancer cells through miR-101-mediated repression of C-terminal binding protein 2 (CtBP2), a corepressor of stemness core genes." (PMID 24429391, 2014). "The results validate CtBP2 as a key modulator of metabolic–epigenetic crosstalk, suggesting that its inhibition can disrupt cancer cell proliferation through redox balance and metabolic regulation; thus, CtBP2 could be a potential therapeutic target in TNBC." (PMID 40710528, 2025). "The increased NADH/NAD+ ratio found in shCtBP2 cells compared to the scrambled control and untransfected MDA-MB231 cells confirms that cancer metabolic rewiring by NADH is involved in the downstream CtBP2 activation and is able to alter the epigenetic landscape." (PMID 34680207, 2021). "There are strong evidences that CTBP2 could promote cancer cell survival and migration/invasion by targeting epithelial and proapoptotic genes and multiple growth inhibitory tumor suppressors." (PMID 34781990, 2021). "In conclusion, our study demonstrated that circHERC4 could act as an oncogenic driver of CRC through a novel circHERC4/miR-556-5p/CTBP2/E-cadherin axis and could be exploited in cancer therapy." (PMID 34781990, 2021). "The observed CtBP2-mediated upregulation of BMI1 in the radioresistant CtBP2 overexpression organoids, could play a role in resistance of cancer cells with elevated CtBP2 to therapeutic chemo-radiation." (PMID 33972635, 2021). "C-terminal binding protein-2 (CtBP2), a transcriptional corepressor, has been reported to correlate with tumorigenesis and progression and predict a poor prognosis in several human cancers." (PMID 28404932, 2017). "C-terminal binding protein-2 (CtBP2) enhances cancer proliferation and metastasis." (PMID 28412731, 2017). "CTBP2 is well known to function as a transcriptional corepressor and modulator of several essential tumorigenic processes, including growth, proliferation, and invasion, in a variety of cancer cells." (PMID 29147064, 2017). "We have recently demonstrated that miRNA-101 increased cancer cell stemness by repressing CtBP2." (PMID 27557510, 2016). "We have previously reported that miRNA-101 increased cancer cell stemness by repressing CtBP2." (PMID 27557510, 2016). "Loss of ARF has been linked to increased cancer cell migration and invasion, and hence weaker cell-cell adhesion, associated with the binding of ARF to the transcriptional corepressor CtBP2 and promoting CtBP2 degradation." (PMID 23555235, 2013). "The high metabolic adaptation ability of CtBP2 knockdown cells revealed in this study suggests how deeper understandings of cancer metabolism might be important in drug design and may lead to more efficient cancer therapies." (PMID 34680207, 2021). "Specifically, CDK7 interacts with C-terminal binding protein 2 (CtBP2), a protein known to promote tumor progression by enhancing epithelial-mesenchymal transition (EMT) and inhibiting apoptosis in cancer cells." (PMID 38605321, 2024). "Third, CtBP2 has been shown to promote epithelial-mesenchymal transition (EMT) and migration of several types of cancer cells." (PMID 37163116, 2023). "MutSigCV analysis identified CDC27, PIK3CA, GATA3, CDH1, CTBP2, and CRIPAK as common cancer driver genes across both Ki67 expression groups (ZF13)." (PMID 37454130, 2023). "For example, CtBP2 can activate Tiam1 (T cell lymphoma Invasion and Metastasis 1) in an NADH-dependent manner, thereby promoting cancer cell migration." (PMID 32549759, 2020).
cancer (continued). "CTBP2, a member of the CTBP family, acts as a transcriptional corepressor to modulate cancer cell growth and tumorigenesis by interacting with the C-terminus of the adenoviral E1A oncoprotein." (PMID 29147064, 2017). "Although the decreased tumor size and metastasis and prolonged survival seen in Ctbp2-deficient CKP mice were accompanied by reduced expression of cancer stem cell markers, the exact mechanism for dependency of PDAC tumor progression on Ctbp2 has remained unclear." (PMID 37949862, 2023). "This study, together with our previous findings, identifies a novel mechanism that CtBP2 transport overexpressed Bcl-xL into the nucleus and nuclear Bcl-xL drives metastasis of cancer cells independent of its anti-apoptotic activity." (PMID 37163116, 2023). "In addition, by qPCR and RNA-seq we identified several cancer-related genes that regulated by AS of APEX1, which included AXIN1, GCNT2, SMAD3, CTBP2, PPARD, and FBXW11." (PMID 35780128, 2022). "Here, CDKN1B, PIAS4, CTBP2, and ABCC1 could be the potential source for ZNF143 to alter the major cancer signaling pathways." (PMID 36675976, 2022). "Moreover, ZEB2 correlates with SMAD1 in 28 cancer types, SMAD2 in 27 cancer types, SMAD3 in 22 cancer types, SMAD5 in 28 cancer types, CTBP1 in 14 cancer types, and CTBP2 in 22 cancer types." (PMID 35723302, 2022). "Based on this result, we could conclude that CDKN1B, PIAS4, CTBP2, and ABCC1 could be the potential source for ZNF143 (because these genes link more biological functions) to alter the major cancer signaling pathways." (PMID 36675976, 2022). "Based on this finding, we might hypothesize that ZNF143’s potential to change the main cancer signaling pathways may originate from CDKN1B, PIAS4, CTBP2, and ABCC1." (PMID 36675976, 2022). "Furthermore, CtBP2 has been described to be overexpressed in several human cancers including CRC, and is involved in oncogenic hallmarks including cancer cell survival and migration." (PMID 33972635, 2021). "While RIBEYE is well known for its role in glutamate release from PR and BC terminals, the role of the shorter CTBP2 isoform has not been extensively studied in the eye but rather from cancer and stem cell studies." (PMID 35095414, 2021). "Ten total RNA samples, with two separate RNA preparations for each of the control, CtBP1-KD, CtBP2-KD, Pinin-KD1 and Pinin-KD2 cancer cell lines, were submitted for cDNA library preparation and massively parallel paired-end multiplex RNA sequencing and analysis as described in Materials and Methods." (PMID 26871283, 2016). "Interestingly, CTBP2 expression also exhibited a negative correlation with activated TILs, which are known to play crucial roles in inhibiting cancer through immune responses." (PMID 38698344, 2024). "In addition we also observed a similar effect for rs4962416, within the gene CTBP2, suggesting that this gene may also be primarily linked to PSA, and not directly to cancer." (PMID 26773531, 2016). "We did not identify any correlations of total gene expression with cancer status for the JAZF1, MSMB, HNF1B, MYEOV or CTBP2 genes." (PMID 20569440, 2010).
tumor (41 papers, 2013 to 2025). "Given that the transcription factors regulated by Ctbp2 are mainly associated with the cell cycle, most studies on Ctbp2 have focused on tumor cells." (PMID 40140769, 2025). "The analysis revealed a significant association between CTBP2 levels and immune cell infiltration within the tumor microenvironment." (PMID 38698344, 2024). "And it is notable that Tet2 knockout in Ctbp2-cKO mice can compensate for Ctbp2 loss in terms of tumor progression." (PMID 37643007, 2023). "Relative to a potential role for CtBP as a key oncogenic driver or dependency, our previous studies have shown that CtBP2 is a dependency for APC mutated neoplasia in the Min mouse intestinal polyposis model of human Familial Adenomatous Polyposis23." (PMID 32332713, 2020). "In this work, we have determined the biologic basis of CtBP2’s neoplastic activities in Apc-mutated neoplasia as linked to its regulation of TIC populations and transcriptional regulation of downstream Wnt targets, such as LGR5, c-Myc and cyclin D1." (PMID 30197752, 2018). "Our recent observations that CtBP2 is a key dependency in Apc-mutated neoplasia, was the first in vivo evidence of CtBP2’s neoplastic potential." (PMID 30197752, 2018). "CTBP2 encodes a transcriptional corepressor that is activated under stress condition and can mediate stress-induced migration of tumor cells." (PMID 24386569, 2013). "Indeed, deletion of Ctbp2 significantly decreased PDAC tumor growth and metastasis and prolonged survival in mice orthotopically implanted with Ctbp2-deficient CKP cells, compared with mice implanted with parental CKP cells." (PMID 37949862, 2023). "CTBP2 functions as a transcriptional corepressor that interacts with transcription factors and chromatin-modifying complexes, primarily acting to repress tumor suppressor genes and those involved in differentiation, apoptosis, and cell cycle regulation." (PMID 41409254, 2025). "We were interested in CtBP2 (C-terminal Binding Protein 2) as a new potential CYR61-downstream effector related to tumor cell dissemination." (PMID 40038783, 2025). "We observed a strong positive correlation between the upregulation of CtBP2 at the invasive tumor front and both the number and the surface area of pulmonary metastatic foci." (PMID 40038783, 2025). "In contrast, CtBP2 signal in cells located at the front area of the tumor derived from CYR61-silenced grafted cells was weakly increased as compared to the core area (+ 29%; p = 0.0178)." (PMID 40038783, 2025). "We thereafter investigated CtBP2 signal intensity in FFPE sections of tumor samples derived from the CYR61-modified cells." (PMID 40038783, 2025). "Our findings shed light on the genome-wide network of OCT1 and AR in AR-positive CRPC and highlight the potential role of CTBP2 in immune response and tumor progression." (PMID 38698344, 2024). "CTBP2 is known as a nuclear transcriptional co-repressor, repressing Wnt target genes and thus leading to tumor suppression." (PMID 36033456, 2022). "Among them, GATA1, RARA and LMO2 were lowly expressed, while E2F4 and CTBP2 were highly expressed in tumor parts." (PMID 35743687, 2022). "For the mechanism, CTBP2 acts as a transcriptional co-repressor and is involved in cell migration, apoptosis and tumor formation." (PMID 35113002, 2022). "Interesting, blast through TCGA tumor cases, patients with CtBP2 genetic alternation had a significantly longer overall survival time than unaltered patients." (PMID 34253710, 2021). "Together these results provided important insights into the fact that CTBP2 was a target gene of miR-556-5p and its overexpression mediated the tumor metastasis through inhibiting E-cadherin in CRC." (PMID 34781990, 2021). "IHC staining showed that the expression of CTBP2 was significantly decreased in the tumor tissues of the sh-circHERC4 groups compared to the sh-NC group in xenograft models." (PMID 34781990, 2021).
tumor (continued). "Mechanistically, we revealed that circHERC4 inactivated the tumor suppressor, miR-556-5p, leading to the activation of CTBP2/E-cadherin pathway which promotes tumor metastasis in CRC." (PMID 34781990, 2021). "This suggests that Ctbp2 plays a crucial role in the transformation from normal stem cells to the tumor-initiating cell phenotype." (PMID 31586042, 2019). "Ctbp2 is a uniquely targetable oncogenic transcriptional coregulator, exhibiting overexpression in most common solid tumors, and critical to the tumor-initiating cell (TIC) transcriptional program." (PMID 31586042, 2019). "Moreover, relative deficiency of Ctbp2, or functional inhibition, in the early progenitor niche in crypts, may suppress Apc-deficiency associated neoplasia, as Ctbp2 is a key component of the pathway between Apc loss and neoplastic transformation, via its regulation of c-Myc and cyclin D1." (PMID 30197752, 2018). "Alphaproteobacteria are significant contributors to our ability to predict mutations in CTBP2, a repressor of transcription known to interact with the ARF tumor suppressor." (PMID 29924794, 2018). "Recently, we have shown that the emerging oncogene and drug target, C-terminal binding protein 2 (CtBP2), is a key driver of neoplasia in the Apcmin/+ (Apcmin) mouse model of human FAP." (PMID 30197752, 2018). "Subsequent multivariate analysis confirmed that CtBP2 (p < 0.001), lymphatic invasion (p < 0.001), tumor size (p = 0.022), and TNM stage (p = 0.018) were independent prognostic indicators for GC patients." (PMID 28404932, 2017). "The results showed that CtBP2 was overexpressed in GC tissues and closely correlated with poor differentiation, advanced tumor stage and poor prognosis in GC patients." (PMID 28404932, 2017). "The level of CtBP2 was positively correlated with the histologic grade (P < 0.001), metastasis (P = 0.046) and tumor size (P = 0.011)." (PMID 28412731, 2017). "The average tumor volume of the control-shRNA group was significantly larger than that of the CtBP2-shRNA#2 group and the GC growth rate in vivo of CtBP2-shRNA#2 group was lower (p < 0.05)." (PMID 28404932, 2017). "The log-rank test indicated that CtBP2 expression (p < 0.001), tumor size (p = 0.028), TNM stage (p < 0.001), vascular invasion (p < 0.001), and lymphatic invasion (p < 0.001) were meaningful prognostic indicators for overall survival." (PMID 28404932, 2017). "C-terminal binding protein-2 (CtBP2) is a transcriptional co-repressor gene involved in tumorigenesis and tumor progression." (PMID 27557510, 2016). "C-terminal binding proteins (CtBPs) encoded by the closely-related genes CTBP2 and CTBP1 mediate transcriptional repression of a number of key tumour suppressor genes." (PMID 24068937, 2013). "Hypoxic conditions in central tumor region interfered with CtBP2 induction of expression." (PMID 40038783, 2025). "To confirm the role of CtBP2 in tumor dissemination we used syngeneic tumor mouse models." (PMID 40038783, 2025). "Additionally, MDSCs inhibit T-cell activation, stimulate the expression of microRNA-101 in ovarian cancer cells by targeting the corepressor CtBP2, and promote tumor stemness." (PMID 41368628, 2025). "Moreover, we reported that CtBP2-silencing significantly impairs tumor dissemination capacity in vivo." (PMID 40038783, 2025). "CtBP2 thus represents an interesting potential target for the prevention of tumor spreading." (PMID 40038783, 2025). "A visual check of the spatial distribution for three of the niche-DE genes (COLGALT1, COL4A1, and CTBP2), each in a separate patient sample, reveals that niche-DE gene expression are indeed enriched in regions of the tissue where fibroblasts and tumor cells colocalize." (PMID 38217002, 2024). "The results showed conspicuously higher CTBP2 expression in tumor tissues." (PMID 37643007, 2023).